CD69 (CD69 molecule)
Diseases named in the same sentence as CD69 in open-access papers (continued):
Sharing a sentence is not in itself a finding about the gene and the disease.
ischemia (3 papers, 2017 to 2022). A hypoperfusion of the BLOOD through an organ or tissue caused by a PATHOLOGIC CONSTRICTION or obstruction of its BLOOD VESSELS, or an absence of BLOOD CIRCULATION. "Cd69–/– mice developed strong IL-17+ γδT cell responses after ischemia that increased myocardial inflammation and, consequently, worsened cardiac function." (PMID 36066993, 2022). "Transfer of CD69+ Treg cells to asthmatic mice has restored immune tolerance, and injection of CD25hi Treg cells has also improved hepatic ischemia-reperfusion injury." (PMID 33334006, 2020).
liver disease (3 papers, 2016 to 2024). "This was further corroborated by correlations of IFNγ production of peritoneal CD8+ T cells and peritoneal CXCR6+CD69+ CD8+ T cells with markers of liver disease severity and renal impairment." (PMID 38882602, 2024). "In conclusion, this study demonstrates that bystander-activated CXCR6+CD69+ CD8+ T cells are abundant in the ascites of patients with decompensated cirrhosis and are associated with liver disease severity." (PMID 38882602, 2024). "•Co-expression of CXCR6 and CD69 identifies distinct clusters of CD8+ T cells that correlate with liver disease severity." (PMID 38882602, 2024). "Since T cell activation is a critical process in the pathophysiology of Con A‐induced liver disease, we then used anti‐CD69 and anti‐CD25 antibodies to measure the amounts of the early or late activated T cells." (PMID 36721037, 2023). "Remarkably, the frequencies of ascites CXCR6+CD69+ CD8+ T cells were significantly correlated with markers of liver disease severity, as indicated by the model for end-stage liver disease score, Child–Pugh score, bilirubin blood levels, and international normalized ratio." (PMID 38882602, 2024). "Of note, IFNγ production by ascites CD8+ T cells correlated with markers of liver disease severity, and this was also true for the CXCR6+CD69+ CD8+ T-cell subset." (PMID 38882602, 2024).
lung fibrosis (3 papers, 2011 to 2022). "CD103+CD69+ tissue RM cells were also suppressive in a murine model of aspergillosis, while CD103–CD69+ resident cells were associated with a proinflammatory phenotype and induction of lung fibrosis." (PMID 35819849, 2022). "For investigating the effects of CD69 deficiency on BLM-induced lung fibrosis, the histopathological changes in the lung were evaluated at 14 dpi." (PMID 21970554, 2011). "Our study identified increased expression of many exosomal surface epitopes (CD19, CD8, CD69, and CD86) in IPF patients with respect to controls, suggesting that an alteration of these markers may be associated with lung fibrosis." (PMID 33925174, 2021). "These facts indicate that CD69 exerts a potential proinflammatory function and may be involved in the pathogenesis of inflammatory diseases such as pulmonary fibrosis." (PMID 21970554, 2011). "Furthermore, lung fibrosis was markedly attenuated in the CD69-/- mice (Figures." (PMID 21970554, 2011).
myocardial infarction (3 papers, 2022 to 2023). Gross necrosis of the myocardium, as a result of interruption of the blood supply to the area, as in coronary thrombosis. "A recent report has also described that CD69+ Tregs, through an AHR-dependent mechanism, express high levels of membrane CD39 in hypoxic conditions after myocardial infarction (MI)." (PMID 37223078, 2023).
neuroblastoma (3 papers, 2021 to 2022). Neuroblastoma (NB) is the most common solid, extracranial childhood tumor. "Using CD69 as a marker of activation in circulating NK cells, CD56dim cells in neuroblastoma patients were more activated, reflecting in vivo activation by the cancer milieu." (PMID 36276144, 2022). "In contrast, circulating NK cells from patients with neuroblastoma had a high frequency of NK cells activated by IL2/15, with IL2 induced CD69 upregulation notably lower." (PMID 36276144, 2022). "Following an 18-h co-culture of CAR-T cells with neuroblastoma target cells, cytotoxic degranulation as determined by CD107a as well as upregulation of CD25 and CD69 activation markers following addition of targets, was non-significantly higher in CD28ζ than 4-1BBζ constructs." (PMID 36159778, 2022).
periodontitis (3 papers, 2021 to 2024). An acute or chronic inflammatory process that affects the tissues that surround and support the teeth. "We also found that salivary exosomal miR-25-3p downregulates CD69 in IL-17-producing γδ T cells, which is implicated in periodontal inflammation and bone loss in obese mice with ligature-induced periodontitis." (PMID 35069547, 2021). "Our MR analysis, using eQTL and pQTL data, identified significant causal relationships between periodontitis and the genes CD93, CD69, and CXCL6." (PMID 39717623, 2024). "The results showed that CD93, CD69, and CXCL6 were all significantly causally associated with the occurrence of periodontitis." (PMID 39717623, 2024). "The findings suggest that CD93, CD69, and CXCL6 are closely related to the progression of periodontitis, with MR confirming their causal links to the disease." (PMID 39717623, 2024). "The results showed significant causal relationships between CD93, CD69, and CXCL6 and periodontitis." (PMID 39717623, 2024). "It is interesting to note that lymphocytes obtained from healthy gingival tissues also expressed higher levels of CD69 expression when compared to the patients with periodontitis." (PMID 33672708, 2021). "When CD16 + NK and CD8+ T cells were treated with IL-2 and PMA/I, higher intensity of CD69 was detected both in OBMCs and PBMCs of periodontitis patients, although the intensity remained higher in OBMCs." (PMID 33672708, 2021). "MR confirmed significant causal relationships between CD93, CD69, and CXCL6 and periodontitis." (PMID 39717623, 2024). "Our findings enhance personalized medicine strategies for periodontitis by identifying key biomarkers CD93, CD69, and CXCL6 and their links to the disease through MR." (PMID 39717623, 2024). "To explore the connections between CD93, CD69, and CXCL6 and periodontitis, we performed single-cell data analysis." (PMID 39717623, 2024). "We conducted a detailed analysis of the expression levels of CD93, CD69, and CXCL6 in normal and periodontitis tissues, revealing that all three genes were significantly upregulated in periodontitis tissues." (PMID 39717623, 2024). "The surface expression levels of CD69 activation antigens were found to be elevated on the CD16 + NK cells and CD8 + T cells in OBMCs when compared to PBMCs of periodontitis patients." (PMID 33672708, 2021). "This suggests that CD93, CD69, and CXCL6 are not only involved in the immune responses driving periodontitis but may also serve as promising therapeutic targets." (PMID 39717623, 2024). "Additionally, to further explore the specific roles of these key genes in the pathological process of periodontitis, we analyzed the cell-type-specific expression patterns of CD93, CD69, and CXCL6 using single-cell RNA sequencing." (PMID 39717623, 2024). "Moreover, increased surface expression levels of CD69 on NK cells were only observed on cells obtained from periodontitis patients and not form the healthy individuals (unpublished material)." (PMID 33672708, 2021).
polyp (3 papers, 2016 to 2022). A usually exophytic mass attached to the underlying tissue by a broad base or a thin stalk. "Analysis of immune cells in polyps and other tissues after short-term C20:2 treatment demonstrated that, similar to C26:0 treatment, there was a significantly increased CD69 expression on CD8 T cells specifically in the polyps, accompanied by decreased proportion of macrophages in polyp and spleen." (PMID 30881361, 2019). "In the absence of stimulation, the expression of CD69 and CD25 on CD8+ T cells in polyp tissues was significantly increased compared with control tissues (P < 0.05)." (PMID 27468819, 2016).
prediabetes (3 papers, 2017 to 2024). "However, a study involving obese subjects with prediabetes or type 2 diabetes undergoing weight loss and energy restriction reported that CD69 expression on TTLy (EATLy) in peripheral blood decreases following BMI reduction." (PMID 39336564, 2024). "The expression of genes involved in human T-cell activation, including CD44 and CD69, as well as proinflammatory cytokines, was significantly higher in patients with prediabetes." (PMID 30867412, 2019).
prostate tumour (3 papers, 2010 to 2022). "The ability of MIL-38-CD3 BiTE to mediate the activation of T cells in the presence of GPC-1-expressing prostate tumour cells was measured by flow cytometry analysis of the early activation marker CD69 and the late activation marker CD25." (PMID 33302918, 2020). "These in vitro findings are further corroborated by our ex vivo data showing the expression IL-12Rβ1 and CD69 on iNKT cells in TRAMP prostate tumors." (PMID 20593019, 2010).
scrub typhus (3 papers, 2016 to 2022). Scrub typhus is a rare dust mite-borne infectious disease caused by the Orientia tsutsugamushi bacterium and characterized clinically by an eruptive fever which is potentially serious. "Finally, our study showed that the impaired production of TNF-α by MAIT cells was associated with elevated CD69 expression in scrub typhus patients." (PMID 27463223, 2016). "Scrub typhus patients had increased NK cell numbers in peripheral blood, increased expression of the activation marker CD69, and enhanced IFN-γ secretion, implying a correlation between NK cell activation and disease severity." (PMID 35479068, 2022). "Percentages of CD69+ NK cells were significantly higher in scrub typhus patients than in HCs (median 14.9% versus 2.9% [p < 0.005])." (PMID 28750012, 2017). "The notion is supported by our observation that plasma levels of IL-12 and IL-18 were increased in scrub typhus patients and that addition of IL-12 and IL-18 upregulated CD69 expression in NK cells." (PMID 28750012, 2017). "We observed that circulating NK cell levels and CD69 expressions increased in scrub typhus patients; thus, we sought to determine circulating NK cell levels and CD69 expressions in the active and remission phases of the illness." (PMID 28750012, 2017). "Scrub typhus patients had significantly higher absolute numbers of CD69+ NK cells than HCs (median 122.7 cells/μL versus 8.2 cells/μL [p < 0.0001])." (PMID 28750012, 2017). "Circulating NK cell levels and CD69 expressions were significantly increased in scrub typhus patients." (PMID 28750012, 2017). "Our study showed that MAIT cells were activated in scrub typhus patients, indicated by CD69 up-regulation." (PMID 27463223, 2016). "Percentages of CD69+ MAIT cells were found to be significantly higher in scrub typhus patients than in HCs (median 36.8% versus 6.0% [p < 0.0001])." (PMID 27463223, 2016). "Thus, we determined cytotoxicities of purified CD69- and CD69+ NK cell subsets in scrub typhus patients by flow cytometry." (PMID 28750012, 2017). "To determine whether NK cells were activated during infection by O. tsutsugamushi, we used flow cytometry to examine the expression of CD69 in circulating NK cells from 31 scrub typhus patients and 18 HCs." (PMID 28750012, 2017). "The present study showed that circulating NK cell levels, together with elevated expression levels of CD69 and IFN-γ, increased in scrub typhus patients." (PMID 28750012, 2017).
Splenomegaly (3 papers, 2007 to 2025). Abnormal increased size of the spleen. "While it was demonstrated that induction of the T-cell early activation marker CD69 in mice results in marked splenomegaly, CD69 knockout mouse spleens were shown to be enlarged compared with those of WT mice in tumor and collagen-induced arthritis challenge models." (PMID 27869695, 2016). "A reduction in CD69 activation has been correlated to both a decrease in splenomegaly and splenic latency in mice infected with γHV68 mutants deficient in vbcl-2, containing a large insertion in the M3 gene, or a modification linking the ORF73 product to a CD8–T-cell epitope." (PMID 17257062, 2007). "However, unlike in Lyn-/-IL-10-/- mice, there was no enhancement of splenomegaly, CD4+ T cell activation (as measured by CD69 expression), CD4 T cell naïve and effector memory frequencies, or myeloid expansion in Lyn-/-.Ighg3-cre.DTA and Lyn-/-.Ighg3-cre.IRF4f/f mice compared to Lyn-/- controls." (PMID 41445737, 2025).
squamous cell carcinoma (3 papers, 2015 to 2025). A carcinoma arising from squamous epithelial cells. "Vice versa, high percentages of CD94+/CD69+ NK cells can control growth of mHsp70-positive squamous cell carcinomas and thus serum levels of Hsp70 are lower." (PMID 26579130, 2015). "Regarding the activation marker CD69, both in CD19+ B lymphocytes and in CD3+CD4+ T lymphocytes, the group with squamous cell carcinoma presented higher percentages, with p indicating differences for CD19+ B lymphocytes (p = 0.01) and T lymphocytes CD3+CD4+ (p = 0.03)." (PMID 40802351, 2025).
thyroid cancer (3 papers, 2021 to 2024). "Similarly with previous study that revealed that activated neutrophils enhance their lysozyme release by crosslinking of CD69, our data revealed that CD69 expression in neutrophils is associated with immunosuppressive phenotype in thyroid cancer." (PMID 38719807, 2024). "Many studies have confirmed the high expression of CD4+ T cells, CD8+ T cells, and CD69 in patients with thyroid cancer such as MTC, which indicates obvious T cell reaction in thyroid cancer patients." (PMID 33414407, 2021).
alopecia areata (2 papers, 2019 to 2021). Loss of scalp and body hair involving microscopically inflammatory patchy areas. "In our systematic literature search, we identified studies showing that CD69+/CD103+ TRMs were increased in lesional skin from the scalp in patients with frontal fibrosing alopecia and alopecia areata, compared with non-lesional and normal scalp skin." (PMID 34445713, 2021).
angina (2 papers, 2014 to 2022). "Before PCI, the CD69 expression was 2.57% [0.98 - 11.51%] on the PBMCs from patients with recurrent angina or restenosis, compared to 1.27% [0.91 - 13.24%] on those from patients without recurrent angina or restenosis (p = NS)." (PMID 25253465, 2014). "Remarkably, the reduction of both CD4 + CD69 + and Treg CD69 + T cells was observed in NSTEMI and STEMI patients but not in stable angina." (PMID 35354890, 2022).
appendicitis (2 papers, 2023 to 2025). Acute inflammation of the vermiform appendix. "Although the decrease in absolute numbers of T cells in complex compared to simple appendicitis suggests a loss of Trms, based on these cross-sectional data, we cannot exclude that the change in percentage of CD69+ T cells is due to an influx of infiltrating T cells." (PMID 38239362, 2023). "In our series, in the appendiceal mucosa, macrophages cell rate (CD163+), T helper lymphocytes (CD4+), T cytotoxic lymphocytes (CD8+) and activated cytotoxic lymphocytes (CD8+CD69+) were all significantly lower in UC patients compared to appendicitis and CC patients." (PMID 40827526, 2025). "Frequencies of phenotypic tissue-resident memory CD69+CD4+ T cells and CD69+CD8+ T cells were decreased in children with complex compared to simple appendicitis, indicating disruption of local tissue-resident immune responses." (PMID 38239362, 2023).
autoimmune hepatitis (2 papers, 2022 to 2025). Hepatitis caused by autoantibodies. "Two of the seven bile samples activated MAIT cells, as measured by increased CD69 and GrB expression: one from a patient with alcohol-related liver disease and one from a patient with autoimmune hepatitis." (PMID 35063408, 2022). "Granzyme B producing cytotoxic CD103+CD69+CD8+ Trm cells could contribute to liver damage in autoimmune hepatitis (AIH)." (PMID 40607400, 2025).
B cell lymphoma (2 papers, 2021 to 2025). "To this end, we established an in vitro assay to measure both cellular viability and expression of the activation marker CD69 by a human mantle VH3+ B cell lymphoma cell line (MAVER-1)." (PMID 34060329, 2021).
bacteremia (2 papers, 2022 to 2025). "Importantly, we found that the CD69 level in T subsets was altered observably according to the subpopulation of underlying bacterial sepsis." (PMID 36703970, 2022). "In contrast to patients with S. aureus bacteremia, there was no increase in the percentage of CD69+ CD56dim NK cells in patients with E. coli bacteremia compared to healthy controls." (PMID 40795240, 2025).
Bladder tumor (2 papers, 2021 to 2022). "Bladder tumor hILC1s had lower expression of NKp30, NKp46, and CD69 compared with hILC2s (p < 0.04), indicating a reduced cytotoxic capacity of hILC1s compared with hILC2s." (PMID 34496133, 2021). "Surprisingly, our results suggested that CD69 (a T cell failure-specific marker) was abnormally expressed in T cells in bladder tumor tissues, however, no significant expression was observed in other cells." (PMID 36211359, 2022).
brucellosis (2 papers, 2019 to 2024). Brucellosis is a bacterial infection that spreads from animals to people via unpasteurized dairy products or by exposure to contaminated animal products or infected animals. "Multiple activation markers, such as CD69, MKI67, CCL5, CTLA4, IFNG and GZMB, were found to be enriched in the NK cells of brucellosis patients, indicating the presence of an activated NK cell response as a distinctive feature for brucellosis patients, especially for those at the acute stage." (PMID 39135683, 2024).
Candidemia (2 papers, 2016 to 2022). A form of invasive candidiasis where species of CANDIDA are present in the blood. "Compared to control patients, CD8 T cells from patients with Candidemia had evidence of cellular activation as indicated by increased CD69 expression while CD4 T cells had decreased expression of the major positive co-stimulatory molecule CD28." (PMID 26786705, 2016). "Similarly, the MFI of CD69 in CD8 T cells from patients with Candidemia was also increased compared to control patients; p <0.01." (PMID 26786705, 2016).
cervical cancer (2 papers, 2016 to 2025). A primary or metastatic malignant neoplasm involving the cervix. "The results showed that TF-BiTE induced T-cell activation more effectively than CD19-BiTE, as evidenced by a higher percentage of CD25+/CD69+ cells in cervical cancer cell lines." (PMID 41009508, 2025).
chronic tonsillitis (2 papers, 2015 to 2017). "To address if T-cells had indeed a constitutively high basal level of activation in chronic tonsillitis, we compared the surface expression of CD69, CD25 and CD154 in freshly isolated tonsillar T-cells." (PMID 28877231, 2017).
depression (2 papers, 2023 to 2024). "Furthermore, the study demonstrates a strong correlation between the severity of depression and elevated numbers of CD4+ CD40L+ and CD4+ CD69+ cells, as well as increased expression of CD40L on CD8+ cells and HLADR on CD3+ cells." (PMID 38750122, 2024).
encephalitis (2 papers, 2010 to 2025). An acute inflammatory process affecting the brain parenchyma. "Specifically, we identified six differentiallyexpressed immune genes—MET, KIT, IL1R2, MAFF, CD69, andCEBPD—between the encephalitis and non-encephalitis groups." (PMID 40985687, 2025).
glomerulonephritis (2 papers, 2021). A renal disorder characterized by damage in the glomeruli. "Similar results were obtained for glomerulonephritis, IgG deposits in kidneys, and the activation status of innate and adaptive immune cells (expression of CD80 and CD69 on cDC2s and CD4+ T cells, respectively)." (PMID 34282144, 2021).